RNU6-848P (RNA, U6 small nuclear 848, pseudogene)
Gene: Small nuclear RNA gene on chromosome 2 (130,622,838 to 130,622,944, forward strand). Ensembl gene ENSG00000251757.
Homologues: Orthologues: macaque U6 (93% identical), macaque U6 (92% identical), guinea pig U6 (77% identical), dog U6 (74% identical), pig U6 (65% identical). Paralogues in human: RNU6-473P (100% identical), RNU6-617P (100% identical), RNU6-1049P (99% identical), RNU6-127P (99% identical), RNU6-1239P (98% identical), RNU6-1268P (98% identical), RNU6-816P (98% identical), RNU6-1021P (93% identical), RNU6-286P (93% identical), RNU6-631P (93% identical), RNU6-749P (93% identical), U6 (93% identical), and 1286 more.